CRP (C-reactive protein)
Diseases named in the same sentence as CRP in open-access papers (continued):
Sharing a sentence is not in itself a finding about the gene and the disease.
Insulin resistance (continued). "In patients with rheumatoid arthritis, inflammatory cytokines (tumor necrosis factor-α and interleukin-6) and C-reactive protein have been shown to be positively correlated with the insulin resistance index (homeostasis model assessment)." (PMID 41464548, 2025). "HOMA IR, homeostatic model assessment of insulin resistance; hs-CRP: high-sensitivity C-reactive protein; HDL C, high-density lipoprotein cholesterol; LDL C, high-density lipoprotein cholesterol; BMI, body mass index." (PMID 40940402, 2025). "TNF-α and IL-6 are key inducers of acute-phase proteins, including CRP, and they impair intracellular insulin signalling, potentially leading to insulin resistance." (PMID 39852378, 2025). "Chronic inflammatory response exacerbates insulin resistance by triggering responses of C-reactive protein (CRP), tumor necrosis factor-alpha (TNF-α), and interleukin-6 (IL-6), resulting in T2DM and renal impairment and increasing uric acid levels." (PMID 40129592, 2025). "CRP has been demonstrated to mediate chronic low-grade inflammation, thereby promoting insulin resistance and β-cell dysfunction." (PMID 41357322, 2025). "Insulin resistance is often accompanied by the release of more pro-inflammatory cytokines from adipocytes, such as tumor necrosis factor-α, C-reactive protein, and interleukin-6, which are commonly found in EMS patients." (PMID 40004998, 2025). "The correlation matrix illustrates the core features of MetS, showing strong positive associations between anthropometric indices, insulin resistance (HOMA-IR and insulin), sdLDL-C, and inflammatory markers (CRP and C3)." (PMID 41155195, 2025). "CRP and WBC were significantly higher in T2DM, reflecting a pro-inflammatory state commonly associated with insulin resistance and vascular risk (p < 0.0001 and p = 0.033)." (PMID 41465784, 2025). "A broader evaluation of metabolic outcomes including insulin resistance, adipokines, and inflammatory markers such as C‐reactive protein (CRP) and interleukin‐6 (IL‐6) would provide a more comprehensive understanding of its systemic effects." (PMID 40887215, 2025). "The mean HOMA-IR was 3.20 ± 1.19, consistent with significant insulin resistance, and CRP was 2.29 ± 1.5 mg/L, reflecting a low-grade inflammatory profile." (PMID 41011029, 2025). "CIMT, carotid intima-media thickness; HOMA IR, homeostatic model assessment of insulin resistance; hs-CRP: high-sensitivity C-reactive protein; HDL C, high-density lipoprotein cholesterol; LDL C, high-density lipoprotein cholesterol; BMI, body mass index." (PMID 40940402, 2025). "ANRIL, non-coding RNA; HOMA IR, homeostatic model assessment of insulin resistance; hs-CRP, high-sensitivity C-reactive protein; HDL C, high-density lipoprotein cholesterol; LDL C, high-density lipoprotein cholesterol; BMI, body mass index." (PMID 40940402, 2025). "Elevated levels of inflammatory cytokines such as tumor necrosis factor α, interleukin 6, and C-reactive protein, commonly associated with FRAILTY and insulin resistance, have been implicated in DR pathogenesis." (PMID 40778361, 2025). "Firstly, in terms of physiological mechanisms, abdominal fat accumulation in men is more likely to trigger insulin resistance and an increase in inflammatory factors (such as CRP), activating the HPA axis and leading to a dysregulation of the stress response." (PMID 41166317, 2025). "These microbial changes correlate with systemic inflammation, elevated IL-6, TNF-α, and CRP, as well as insulin resistance (HOMA-IR)." (PMID 40308637, 2025). "Exercise reduces the levels of pro‐inflammatory biomarkers such as C‐reactive protein (CRP), interleukin‐6 (IL‐6) and tumour necrosis factor‐alpha (TNF‐α), which are associated with insulin resistance and cardiovascular diseases." (PMID 40371883, 2025). "BAR had lower levels of inflammation and insulin resistance compared to CON (CRP: 0.87 ± 1.21 mg/L vs. CON 1.86 ± 1.80, p < 0.01; HOMA‐IR: 2.8 ± 2.3 vs. 5.0 ± 3.9, p < 0.001)." (PMID 40468919, 2025).
Insulin resistance (continued). "Considerably, hormonal imbalances, such as insulin resistance, altered adipokines, and inflammatory markers like highly sensitive-reactive protein (hs-CRP), IL-6, and TNF-α, are pivotal in fatty liver pathogenesis and cardiovascular risk." (PMID 39808219, 2025). "Studies have found a higher incidence of elevated CRP levels in PCOS patients with insulin resistance and obesity." (PMID 39858445, 2025). "Elevated CRP levels, in turn, reflect a state of systemic inflammation that interferes with metabolic processes, worsening insulin resistance and promoting further adiposity." (PMID 40547317, 2025). "Lean diabetics exhibited distinct biochemical features - higher adiponectin but elevated CRP and IL-6 - supporting inflammation and β-cell dysfunction as key drivers over insulin resistance." (PMID 41523554, 2025). "CRP, a well-established inflammatory marker, has been shown to activate NF-κB signaling, promote cytokine release, and contribute to insulin resistance." (PMID 40981199, 2025). "Research has established that VAT contributes to metabolic dysregulation, primarily through its role in insulin resistance and the secretion of various inflammatory factors, including interleukin-6 (IL-6) and C-reactive protein (CRP)." (PMID 39319256, 2024). "The two cohorts were age-matched, but subjects with PCOS had a greater body mass index (BMI), increased insulin resistance, hyperandrogenemia and increased C-reactive protein (CRP, an inflammatory marker)." (PMID 38256230, 2024). "Second, the impact of inflammatory cytokines such as IL-6 and CRP is worth considering; these cytokines exacerbate atherosclerosis and insulin resistance, which are key mechanisms in CVD development." (PMID 38698329, 2024). "Higher triglycerides were accompanied by higher levels of LDL cholesterol, HOMA for insulin resistance, C-reactive protein, body mass index, systolic blood pressure, and total cholesterol, as well as lower levels of HDL cholesterol." (PMID 38611646, 2024). "Elevated CRP impairs leptin function, potentially disrupting satiety signals and promoting metabolic dysregulation, including insulin resistance." (PMID 39770957, 2024). "It was also discovered that patients with polycystic ovary syndrome had significantly higher levels of serum C-reactive protein, homeostasis model assessment of insulin resistance, and total testosterone compared to the control group." (PMID 38397957, 2024). "Methylation of PRKCZ in the underfed group negatively correlated with INSR and IRS1 expression, and positively with CRP, showing a relationship between methylation and inflammatory and insulin resistance markers." (PMID 38256201, 2024). "Research indicates that the METS-IR index is positively correlated with levels of inflammatory markers like CRP and IL-6, suggesting that higher insulin resistance corresponds to stronger inflammatory responses." (PMID 39514584, 2024). "The significant association between C. pneumoniae seropositivity and higher BMI and metabolic syndrome also suggests that CRP plays an active role in the development of insulin resistance." (PMID 39768981, 2024). "Among these, leptin, adiponectin, CRP, TNF-α, and resistin are closely associated with the occurrence and development of insulin resistance." (PMID 40302954, 2024). "The majority (34%) of studies listed the measurement of established markers in routine clinical use, such as insulin resistance, serum oestradiol, liver fat content, and C-reactive protein, as the primary outcome measure." (PMID 38255828, 2024). "Aspartate aminotransferase, alanine aminotransferase, and C-reactive protein levels significantly decreased in all groups, and insulin resistance improved in the middle and high groups but worsened in the low group." (PMID 39006362, 2024).
Insulin resistance (continued). "In conclusion, abdominal obesity, insulin resistance, elevated CRP levels, hyperglycemia, hypertriglyceridemia, and higher heart/pulse rates should all be considered potential harbingers of adverse cardiometabolic outcomes." (PMID 39121088, 2024). "Ingestion of a high diet for 10 weeks induced a clear elevation in BMI, AC/ TC, insulin resistance, hyperlipidemia, CRP, CPK-MB, and cTnI in all HFD groups." (PMID 38316807, 2024). "Higher CRP concentrations were observed in individuals with insulin resistance, dyslipidemia, and MetS." (PMID 39452916, 2024). "For instance, C-reactive protein (CRP) levels are elevated in patients with insulin resistance, T1DM, and T2DM." (PMID 38255878, 2024). "It was also associated with aggravated functional and biochemical parameters (lower handgrip strength, higher BMI, insulin resistance, and increased CRP, creatinine, triglycerides, and uric acid levels), particularly in the eldest." (PMID 39302236, 2024). "High levels of inflammatory markers like C-reactive protein (CRP), interleukin-6 (IL-6), and tumour necrosis factor-alpha (TNF-α) are strong predictors of CVD risk and are also associated with insulin resistance and metabolic syndrome." (PMID 38999799, 2024). "It directly influences HTN, CRP levels–suggesting an impact on the body’s inflammation levels –, and insulin resistance, as measured by HOMA-IR." (PMID 39717478, 2024). "Raspberry consumption did not have a significant effect on fasting blood glucose, insulin, hemoglobin A1C, glucose tolerance tests, homeostatic model assessment for insulin resistance, C-reactive protein, and interleukin-6 concentrations." (PMID 38860149, 2024). "In males, elevated CRP levels impacted leukocyte counts similarly to central obesity combined with insulin resistance in subjects with low CRP levels." (PMID 38255379, 2024). "It is equally plausible that hyperglycemia induced CRP secretion contributing to inflammation as it is that increased CRP secondary to an unrelated source of inflammation-induced insulin resistance that affected glucose metabolism." (PMID 39234180, 2024). "Their results also were positively correlated with BMI, serum TG, glucose, C-reactive protein, and the degree of insulin resistance." (PMID 39030467, 2024). "Inflammatory factors such as TNF-α, IL-6, and C-reactive protein are known to contribute to insulin resistance in GDM." (PMID 39759105, 2024). "In that study, the researchers also noted a significant positive correlation between oncostatin M levels and both C-reactive protein and homeostasis model assessment of insulin resistance values." (PMID 38397957, 2024). "Mediation analyses used serum high‐sensitivity C‐reactive protein (hs‐CRP) and homeostatic model assessment for insulin resistance (HOMA‐IR) as mediators." (PMID 39378156, 2024). "Vitamin D3 deficiency has been linked to increased C-reactive protein (CRP), hyperlipidemia, insulin resistance, blood flow changes, and atherosclerosis." (PMID 38715605, 2024). "Visceral adiposity resulting from insulin resistance led to an imbalance in the secretion of IL-6 and CRP inflammatory mediators." (PMID 39221158, 2024). "Moreover, individual factors associated with MetS have been associated with different mechanisms in insulin resistance, aromatase activity, adipokine secretion, angiogenesis, high CRP levels, glucose use, and oxidative stress and its consequent DNA impairment, which together may enhance cancer risk." (PMID 38785834, 2024). "Spinach aids insulin resistance by inhibiting increased levels of serum C-reactive protein, tumor necrosis factor (TNF)-α, and Interleukin-6." (PMID 39519546, 2024).
Insulin resistance (continued). "In our previous study, we developed a new indicator of inflammatory insulin resistance indicator, the CRP-TyG index (CTI), which can better predict the prognosis of patients with cancer." (PMID 38273418, 2024). "More precisely, CRP induces insulin resistance by activating the MAPK signaling pathways or interfering with the IRS/PI3K/AKT signaling pathway (insulin receptor substrate/phosphatidylinositol 3 kinase/AKT)." (PMID 39430749, 2024). "A negative correlation was found between oncostatin M levels and both homeostasis model assessments of insulin resistance and C-reactive protein levels in our study." (PMID 38397957, 2024). "We also investigated serum lipids and high-sensitive C-reactive protein levels and calculated the homeostatic model assessment-insulin resistance indices and adipokine levels as predictive biomarkers." (PMID 39683642, 2024). "Studies have shown that inflammation, characterized by increased C-reactive protein (CRP), is closely related to insulin resistance." (PMID 39340004, 2024). "Outcomes included weight, weight retention, body composition, insulin resistance and secretion indices, C reactive protein (CRP), and bone density." (PMID 38772880, 2024). "High systemic levels of C-reactive protein (CRP), cytokines, chemokines, and growth factors are induced by insulin resistance." (PMID 39200115, 2024). "A total of 39 targets were positively correlated with FPG, but none of the tested targets were correlated with insulin, C-reactive protein (CRP) or Homeostatic Model Assessment of Insulin Resistance (HOMA-IR) levels." (PMID 39000149, 2024). "Further correlation analyses of values at baseline demonstrated correlations between IAPP levels and various metabolic and inflammatory plasma markers, in particular insulin, insulin resistance, CRP, and GGT." (PMID 39062913, 2024). "As an important regulator of CRP, IL-6 induces insulin resistance and dyslipidemia, and is directly related to the consequences of vascular lesions." (PMID 40302954, 2024). "The Insulin Resistance Atherosclerosis Study (IRAS) showed that insulin resistance was significantly related to higher CRP levels." (PMID 39687453, 2024). "Insulin-sensitive non-diabetics and prediabetic individuals did nothave higher CRP levels than individuals who were both insulin resistance and prediabetic.These variations were believed to be somewhat caused by variations in body weight." (PMID 39132231, 2024). "Significant differences were observed among these groups in body weight; BMI; WC; systolic blood pressure; and albumin, FBG, HbA1c, TG, HDL-C, AST, ALT, insulin, insulin resistance, and hs-CRP levels." (PMID 39408311, 2024). "We also assessed insulin resistance, body mass indices (BMI), waist/hip ratios, comprehensive metabolic and lipid panels, and CRP levels." (PMID 39121088, 2024). "After the investigation, body weight, fasting blood sugar (FBS), irisin, insulin, C‐reactive protein (CRP), interleukin‐6 (IL‐6), interleukin‐1 beta (IL‐1β), leptin, adiponectin, and insulin resistance (IR) were assessed." (PMID 39479712, 2024). "Tumor necrosis factor-α and interleukin (IL)-6 are derivatives of acute-phase proteins, including CRP, and both potentially contribute to insulin resistance by affecting intracellular insulin signaling." (PMID 37448125, 2023). "Insulin resistance was assessed by homeostasis model assessment-insulin resistance score (HOMA-IR) (cutoff: ≥2.5), subclinical inflammation was estimated by ferritin/CRP/uric acid, and cardiovascular risk was assessed using SCORE2/ASCVD." (PMID 37842290, 2023). "It has been demonstrated that inflammatory factors, including IL-1, TNF-α, CRP, and MCP-1, are linked to tissue insulin resistance, and this relationship is mediated by the JNK and NF-кB pathways." (PMID 37876013, 2023). "Fat cells enhance insulin resistance and metabolic disorders, thereby promoting inflammation by increasing levels of CRP and other inflammatory markers." (PMID 36900791, 2023).
Insulin resistance (continued). "In this study, both the combination group and the selenium-only group experienced a significant improvement in markers of inflammation (hs-CRP), oxidative stress (glutathione), and insulin resistance (insulin, HOMA-IR, and QUICKI)." (PMID 36984879, 2023). "The result of the present study further demonstrates that the concentration of CRP increases with increasing levels of insulin resistance during prediabetes." (PMID 38024366, 2023). "Several reports have revealed that inflammatory molecules such as interleukin 6 (IL-6), tumor necrosis factor-α (TNF-α), and C-reactive protein (CRP) are elevated in individuals with T2DM and associated with insulin resistance." (PMID 37445656, 2023). "The increase of proinflammatory cytokine IL-6 after surgery is related to insulin resistance, and its sensitivity is higher than CRP." (PMID 37928355, 2023). "GDF-15 concentrations have been reported to positively correlate with age, BMI, W/H ratio, adiposity, glucose, degrees of insulin resistance, and CRP." (PMID 37436597, 2023). "At 1 year postpartum, CRP correlated with weight, body fat and indices of insulin resistance and secretion (all p ≤ 0.014)." (PMID 37891561, 2023). "Anthropometric indices, aerobic performance, insulin resistance and sensitivity, lipid profiles, testosterone, cortisol and hs-CRP were evaluated." (PMID 36978202, 2023). "C-reactive protein is related to insulin resistance and hyperglycemia, and hyperglycemia and elevated C-reactive protein levels are also associated with the development of diabetic nephropathy." (PMID 37370958, 2023). "Several studies have found that H. pylori upregulates the expression of various inflammatory factors, including C-reactive protein, tumor necrosis factor, various interleukins, and promotes insulin resistance levels." (PMID 36819677, 2023). "Second, some clinical parameters were not included in the present study, such as uric acid, HbA1C, C-reactive protein and homeostasis model assessment for insulin resistance (HOMA-IR)." (PMID 37189508, 2023). "On the other hand, a reduction in CRP levels is observed with folic acid supplement use, as well as improvement in adiponectin levels and insulin resistance with vitamin B12 supplement use." (PMID 36520252, 2023). "The patients with Mets, comparing with those without Mets, have significantly shorter duration of HD, higher high-sensitive C-reactive protein, and higher Homeostatic Model Assessment for Insulin Resistance (HOMA-IR)." (PMID 36983240, 2023). "During pregnancy, obese women showed increased insulin resistance, increased leptin and CRP levels, and decreased FT4 and adiponectin levels, which are associated with increased risk of cardio-metabolic pregnancy complications such as GDM and preeclampsia." (PMID 36520252, 2023). "The green cluster includes keywords such as oxidative stress, metabolic syndrome, insulin resistance, adipose tissue, blood pressure, cholesterol, inflammation, and C-reactive protein." (PMID 37342553, 2023). "FGF23 is associated with inflammation through IL-6 (interleukin 6), IL-10 (interleukin 10), and CRP (C-reactive protein) and with symptoms of metabolic syndrome: insulin resistance, visceral obesity, and dyslipidemia." (PMID 38139126, 2023). "Correlation and linear regression analysis between insulin resistance markers with C-reactive protein and plasminogen activator inhibitor -1." (PMID 38024366, 2023). "The two cohorts were age-matched, but subjects with PCOS had a greater BMI, had increased insulin resistance, hyperandrogenemia, and increased C-reactive protein (CRP, an inflammatory marker)." (PMID 36980195, 2023). "Around four months postpartum, CRP levels correlate with hepatic insulin resistance in women with GDM." (PMID 37891561, 2023). "For the obese cohort, age was matched, but PCOS subjects had a greater BMI, showed increased insulin resistance, hyperandrogenemia and increased CRP (as a marker of inflammation)." (PMID 37566081, 2023).